RIPK1 (receptor interacting serine/threonine kinase 1)
Diseases named in the same sentence as RIPK1 in open-access papers (continued):
Sharing a sentence is not in itself a finding about the gene and the disease.
systemic inflammatory response syndrome (27 papers, 2014 to 2025). SIRS is a serious condition related to systemic inflammation, organ dysfunction, and organ failure. "Treatment with Zharp1-163 in mice can alleviate TNF-α-induced RIPK1-driven systemic inflammatory response syndrome (SIRS)." (PMID 40877228, 2025). "We then identified Ibrutinib as an inhibitor of RIPK3 and found that Quizartinib protected against the TNF-induced systemic inflammatory response syndrome in mice by inhibiting the activation of RIPK1." (PMID 37741898, 2023). "RIPK1 inhibition is also protective in acute disease models such as the TNF-induced systemic inflammatory response syndrome (SIRS) model." (PMID 32999468, 2021). "Others, TNF-induced systemic inflammatory response syndrome, and even metastasis in cancer cells were also closely related to RIPK1 kinase activation." (PMID 34745415, 2021). "Recent studies suggest that RIPK1 inhibition would fundamentally improve the therapy of RIPK1-dependent organ damage in stroke, myocardial infarction, kidney failure, and systemic inflammatory response syndrome." (PMID 33273695, 2021). "Of note, these mice were also greatly protected from a lethal dose of TNF injected in absence of IKKi, a model of Systemic Inflammatory Response Syndrome (SIRS) also caused by RIPK1 kinase-dependent apoptosis and necroptosis." (PMID 30988283, 2019). "Nevertheless, both approaches indicate that RIPK1/RIPK3-mediated cellular damage by necrosis drives mortality during TNFα-induced systemic inflammatory response syndrome (SIRS)." (PMID 27048815, 2016). "Additionally, Phen mitigated RIPK1-driven inflammation in a murine model of systemic inflammatory response syndrome (SIRS) induced by lipopolysaccharide (LPS) and tumor necrosis factor (TNF)." (PMID 40456737, 2025). "Moreover, mice with kinase-dead RIPK1 knock-in mutations are resistant to TNF-induced necroptosis and systemic inflammatory response syndrome (SIRS), similar to RIPK3 knockout mice, and demonstrate superior resistance compared to MLKL knockout mice." (PMID 39062098, 2024). "We also found that Quizartinib inhibited the activation of RIPK1 and protected mice from TNF-induced systemic inflammatory response syndrome (SIRS)." (PMID 37741898, 2023). "Knock-in mice expressing UBA domain-mutant cIAP1 are more sensitive to TNF-mediated systemic inflammatory response syndrome (SIRS), implying that UBA domain-mediated RIPK1 K48-linked ubiquitination is an important step in modulating the cytotoxic potential of the TNF-mediated response." (PMID 34075202, 2021). "In RIPK1- and RIPK3-dependent processes, necroptosis mediates TNF-induced systemic inflammatory response syndrome." (PMID 32366830, 2020). "Studies on mouse models of the TNF-induced systemic inflammatory response syndrome (SIRS) and CLP-induced peritoneal sepsis have shown that multiple organ failure and animal mortality are driven by both RIPK1 and RIPK3-dependent necroptosis." (PMID 25140116, 2014). "In the absence of a functional UBA domain of cIAP1, more active RIPK1 kinase accumulates in response to TNF, causing RIPK1 kinase-mediated cell death and systemic inflammatory response syndrome." (PMID 29452637, 2018). "In the absence of a functional UBA domain, more active RIPK1 kinase accumulates in response to TNF, causing RIPK1 kinase-mediated cell death and systemic inflammatory response syndrome." (PMID 29452637, 2018). "Necroptosis has been reported to drive systemic inflammatory response syndrome (SIRS), while necroptosis inhibition by genetic means (e.g., deletion in RIPK3 gene) or by pharmacological means (RIPK1 inhibition by necrostatin-1) protects against SIRS." (PMID 36611990, 2023). "Studies on mouse models have also shown that TNF-induced systemic inflammatory response syndrome (SIRS) and CLP-induced peritoneal sepsis are driven by both RIPK1 and RIPK3-dependent necroptosis." (PMID 26491219, 2015).
systemic inflammatory response syndrome (continued). "Both RIPK1 kinase-driven inflammation and cell death are key contributors to tumour necrosis factor-alpha (TNF-α)-induced systemic inflammatory response syndrome (SIRS)." (PMID 38419035, 2024). "To demonstrate scalability, we used automated immunohistochemistry to characterize the expression of Caspase-8, RIPK1 and RIPK3 across six tissues during TNF-induced systemic inflammatory response syndrome (SIRS)—a widely-used model of RIPK-dependent pathology." (PMID 38750308, 2024). "Several type II kinase inhibitors such as the FDA approved drugs ponatinib and sorafenib, which target RIPK1, also block the kinase activity of RIPK3 and can protect mice from TNF-induced systemic inflammatory response syndrome (SIRS) and renal ischemia-reperfusion injury." (PMID 37409125, 2023).
Yersinia infection (27 papers, 2016 to 2026). "During Yersinia infection, a network of interactions emerges, with RIPK1 co-immunoprecipitating key cell death regulators like ASC, RIPK3, FADD, Caspase-8, and NLRP3." (PMID 41479920, 2025). "On the other hand, in macrophages that have been primed by TNFR1/TLR signaling prior to Yersinia infection, RIPK1 is inhibited, and pyrin is produced, and thus the translocated effectors YopE/T selectively trigger the pyrin inflammasome ETI." (PMID 39883598, 2025). "Currently, studies have only demonstrated the TAK1-regulated activation and assembly mechanism of the RIPK1-PANoptosome in Yersinia infection." (PMID 39544942, 2024). "The IFN-ɣ inducible Z-DNA binding protein, ZBP1, has been shown to play a role in the assembly of the RIPK1-TRIF-caspase-8 complex in response to Yersinia infection." (PMID 39513865, 2024). "As a consequence, mice expressing the S25D-RIPK1 mutant fail to activate RIPK1-dependent cell death and are defective in defending against Yersinia infection, similar to the mice expressing the RIPK1 kinase-dead mutant K45A." (PMID 39062098, 2024). "In murine BMDMs, TNF or TLR stimulation together with pharmacological TAK1 or IKK blockade induces RIPK1- and caspase-8-dependent cell death, similar to Yersinia infection." (PMID 39186805, 2024). "A recent study revealed that Yersinia infection induces PANoptosis activation in macrophages, combined with the formation of a RIPK1-PANoptosome complex, which includes RIPK1, RIPK3, caspase-8, NLRP3, ASC, and caspase-1." (PMID 38129399, 2023). "Recently, Yersinia infection was found to activate PANoptosis, with infection inducing the formation of a PANoptosome containing RIPK1, RIPK3, caspase-8, ASC, FADD, and NLRP3." (PMID 35563804, 2022). "PANoptosomes have also been identified by immunoprecipitation during Yersinia infection, where RIPK1, RIPK3, caspase-8, FADD, ASC, and NLRP3 can be co-immunoprecipitated." (PMID 35563804, 2022). "Together, these results indicate that inhibition of hematopoietic Ser25 phosphorylation of RIPK1 by YopP/J activates a backup mechanism consisting in RIPK1 kinase-dependent cell death that is required for proper immunity to Yersinia infection." (PMID 30988283, 2019). "Consistent with this, a recent report highlighted that RIPK1-dependent caspase-8 activation leads to GSDMD cleavage and pyroptosis in response to Yersinia infection and that alternative pathways including caspase-11 are recruited when RIPK1 or caspase-8 is impaired." (PMID 41596270, 2026). "Research has demonstrated that Yersinia infection can induce RIPK1-independent PANoptosis." (PMID 41479920, 2025). "Importantly, RIPK1 kinase activity is critical for caspase-8-dependent cell death, restriction of bacterial loads, and host survival during Yersinia infection in mice." (PMID 39186805, 2024). "Furthermore, Yersinia infection also modulates RIPK1-dependent apoptosis and necroptosis, concurrently with pyroptosis activation, thus triggering PANoptosis." (PMID 39062098, 2024). "Immunoprecipitation revealed that RIPK1 co-precipitates with RIPK3, caspase-8, ASC, FADD, and NLRP3 during Yersinia infection, suggesting that RIPK1 may form a PANoptosome with these key cell death components." (PMID 39544942, 2024). "Furthermore, we demonstrate that activation of RIPK1-dependent pyroptosis in neutrophils during Yersinia infection requires IFN-γ priming, which serves to induce surface TNFR1 expression and amplify soluble TNF secretion." (PMID 38965211, 2024). "In the context of Yersinia infection, RIPK1 is necessary for activation of caspase-1, GSDMD, caspase-8, caspase-3, and caspase-7, but it negatively regulates the activation of MLKL, highlighting the multifaceted modulation of cell death effectors that can occur within PANoptosis." (PMID 35563804, 2022). "A previous study has shown that Yersinia infection can inhibit TAK1 to phosphorylate RIPK1 and activate RIPK1-PANoptosis." (PMID 39979525, 2025).
Yersinia infection (continued). "Of note, the RIPK1-PANoptosome assembles in the absence or under the inhibition of TAK1 and during Yersinia infection." (PMID 41263557, 2025). "For example, in the Gram-negative bacteria Yersinia infection, RIPK1-dependent activation of Caspase-8 cleaves gasdermin D and E, inducing pyroptosis in mouse macrophages." (PMID 39062098, 2024). "Here, we report that unlike in murine macrophages, RIPK1 is dispensable for cell-extrinsic apoptosis in human macrophages during Yersinia infection or pharmacological blockade of IKK." (PMID 39186805, 2024). "Here, we report that, in contrast to murine systems, Yersinia infection or chemical blockade of immune signaling in human cells induces a distinct apoptotic cell death that is entirely independent of RIPK1 kinase activity." (PMID 39186805, 2024). "In myeloid cells, acetyltransferase Yersinia outer protein J (YopJ) activated GSDME but not GSDMD by promoting RIPK1/caspase-8 pathway to induce myeloid cell pyroptosis and protect host from Yersinia infection." (PMID 38022612, 2023). "In further support of the importance of the TRIFosome in Yersinia infection, cleavage of CASP8 was inhibited nearly entirely in the absence of TRIF, and partially in the absence of ZBP1 and RIPK1 kinase activity in the context of high MOI Yersinia infection." (PMID 33397971, 2021). "This is likely due to the activity of YopJ in the context of Yersinia infection, which potently inhibits the IKK complex, and therefore likely impacts the ability of IKK complex to provide a transcription-independent prosurvival signal to RIPK1." (PMID 27737018, 2016). "However, as with Yersinia infection, this cell death was not blocked by Nec-1, indicating that RIPK1 activity was not required." (PMID 39186805, 2024). "However, studies show that knocking out RIPK1 during Yersinia infection does not fully prevent cell death." (PMID 39544942, 2024).
COVID-19 (26 papers, 2021 to 2025). A disease caused by infection with severe acute respiratory syndrome coronavirus 2. "RIPK1-mediated inflammatory response has also been shown to be involved in severe cases of Coronavirus disease 2019 (COVID-19) caused by severe acute respiratory syndrome coronavirus 2 (SARS-CoV-2)." (PMID 36969188, 2023). "Cells stimulated with TNF-α and IFN-γ show MLKL and RIPK1 phosphorylation, suggesting that necroptosis is implicated in the COVID-19 cytokine storm." (PMID 34594225, 2021). "A study found that TNF-α and IFN-γ synergism mediated RIPK1/FADD/CASP8 axis-derived PANoptosis in murine bone marrow-derived macrophages (BMDMs) drives pathology in COVID-19 and other diseases associated with cytokine storm." (PMID 34594225, 2021). "The effect of primidone for the treatment of other inflammatory diseases may also be considered, since the activation of RIPK1 has been implicated in mediating a variety of inflammatory diseases including COVID-19-associated cytokine release syndrome (CRS)." (PMID 38086800, 2023). "Overall, these data support the rationale for RIPK1 inhibition as a potential therapeutic option for the treatment of COVID-19." (PMID 38419035, 2024). "Another study of critically ill COVID-19 patients found significantly higher levels of serum RIPK1 than in healthy controls, with differences observed in relation to disease severity." (PMID 37090690, 2023). "Proteome-wide data and RNA-sequencing data suggested that RIPK1 was the candidate anti-COVID-19 therapeutic targets for these cases." (PMID 37726282, 2023). "The important role of RIPK1 kinase in the pathogenesis of COVID-19 has also been revealed by proteome-wide data analysis, which suggests RIPK1 as a promising drug target to rescue multiorgan injury and inflammation in COVID-19." (PMID 39872161, 2022). "RIPK1 inhibitor is currently being tested in human clinical trials for COVID-19 treatment (NCT04469621)." (PMID 36494757, 2022). "Biomarkers of the receptor-interacting serine/threonine-protein kinase 1 (RIPK1) activity have been identified in lung pathology samples from patients with COVID-19." (PMID 35527821, 2022). "RIPK1 kinase activation has been found in human COVID-19 lung pathological samples, cultured human lung organoids and lung section of human ACE2 transgenic mice infected by SARS-CoV-2." (PMID 39872161, 2022). "RIPK1 driven neutrophil necroptosis was identified in critically ill COVID-19 patients, and RIPK1 activation was detected in lungs of COVID-19 patients which was at least in part a result of infiltration of RIPK1+ macrophages and neutrophils." (PMID 35244141, 2022). "A clinical study of primidone in the treatment of COVID-19 by blocking RIPK1 is currently under application to the European Union’s Drug Regulatory Agency Clinical Trials Database (EudraCT)." (PMID 36494757, 2022). "Recently, RIPK1 activation was described in human COVID-19 lung samples; inhibition of RIPK1 with the use of small molecules reduced lung viral load and mortality in ACE2 transgenic mice." (PMID 36466830, 2022). "The activation of RIPK1 was found in human COVID-19 pathological samples, and human lung organoids and ACE2 transgenic mice infected by SARS-CoV-2." (PMID 34663909, 2021). "Immunohistochemical analyses of pharyngeal epithelial cell samples from COVID-19 patients revealed high rates of cells positive for active phosphorylated RIPK1." (PMID 33273695, 2021). "Since activation of RIPK1 can promote necroptosis, apoptosis and inflammation, we investigated each of these three possibilities by examining their biomarkers in COVID-19 lungs." (PMID 34663909, 2021). "We found evidence of RIPK1 activation in human COVID-19 lung pathological samples, and cultured human lung organoids and ACE2 transgenic mice infected by SARS-CoV-2." (PMID 34663909, 2021). "RIPK1 inhibitors are available and have already entered clinical testing suggesting potential therapeutic options for COVID-19 as well as for incontinentia pigmenti." (PMID 34675436, 2021).
COVID-19 (continued). "Strikingly, immunohistochemical analyses of all epithelial cell samples from the COVID-19 patients were positive for active phosphorylated RIPK1." (PMID 33273695, 2021). "Consistent with the activation of RIPK1 by SARS-CoV-2 infection in the lungs of COVID-19 patients, activated RIPK1 was also found in the lungs of SARS-CoV-2-infected AC70 transgenic mice and was reduced in the lungs of the mice treated with Nec-1s." (PMID 34663909, 2021). "Taken together, these data suggest the therapeutic potential of RIPK1 inhibitors for the treatment of severe COVID-19 — not only for inhibiting inflammatory cytokine storm, but also for reducing viral loads." (PMID 34663909, 2021). "Our data support further clinical studies of a RIPK1 inhibitor for the treatment of severe COVID-19." (PMID 34663909, 2021). "Here, we examined the role of RIPK1 in SARS-CoV-2 infection using human COVID-19 lung pathological samples, cultured human lung organoids and ACE2 transgenic mice." (PMID 34663909, 2021). "Strikingly activated RIPK1 were enriched in ciliated epithelial cells in the airways of severe COVID-19 patients which corresponded to elevated levels of proinflammatory cytokines in the BALF, lung and PBMCs in patients as compared to that of control individuals." (PMID 38419035, 2024). "RIPK1 activation was found in the upper respiratory epithelial cells of COVID-19 patients." (PMID 36494757, 2022). "In conclusion, targeting necroptosis and RIPK1 kinase may be a promising strategy to treat aging-related severe COVID-19 patients." (PMID 39872161, 2022). "They found that expression of receptor interacting serine/threonine-protein kinase 1 (RIPK1), an important mediator of inflammation and cell death, is upregulated in patients with COVID-19 who experience a cytokine storm, and is also activated in SARS-CoV-2-infected primary LOs." (PMID 35912110, 2022). "Since the phosphorylation of MLKL is mediated by RIPK3 in necroptosis, the low-level expression of RIPK3 in COVID-19 lung may preclude the activation of MLKL downstream of activated RIPK1 to promote necroptosis." (PMID 34663909, 2021). "The finding that RIPK1 is activated during COVID-19, together with its implication in the pathogenesis of many human inflammatory diseases, makes RIPK1 an attractive drug target for ameliorating or suppressing the lethal CRS associated with SARS-CoV-2 infection." (PMID 33273695, 2021). "Therefore, our data warrant a clinical trial to assess the benefit of RIPK1 inhibition in patients with COVID-19." (PMID 33273695, 2021). "In addition, the increase of RIPK1+ cells in severe COVID-19 lungs is in part due to infiltrating macrophages and neutrophils which express high levels of RIPK1." (PMID 34663909, 2021). "Our results suggest that SARS-CoV-2 may have an unexpected and unusual ability to hijack the RIPK1-mediated host defense response to promote its own propagation and that inhibition of RIPK1 may provide a therapeutic option for the treatment of severe COVID-19." (PMID 34663909, 2021). "In this scenario, the use of Nec-1/Nec-1 analogues might alleviate cytokine storm, systemic inflammation, and COVID-19 thanks to its activity to block RIPK1, the molecule that interacts with RIPK3 and promotes the phosphorylation of MLKL." (PMID 34201847, 2021). "RIPK1 is expressed in epithelial cells and macrophages in both control and COVID-19-positive lungs." (PMID 34663909, 2021). "We found a strikingly enriched presence of activated RIPK1 in the ciliated epithelial cells in the airways of severe COVID-19 patients which corresponds to elevated levels of proinflammatory cytokines and factors in the BALF, lung and PBMCs in patients compared to that of control individuals." (PMID 34663909, 2021).